HMGCS2 (3-hydroxy-3-methylglutaryl-CoA synthase 2)
Diseases named in the same sentence as HMGCS2 in open-access papers (continued):
Sharing a sentence is not in itself a finding about the gene and the disease.
colorectal cancer (10 papers, 2017 to 2024). A primary or metastatic malignant neoplasm that affects the colon or rectum. "In this study, we demonstrate that HMGCS2 mRNA expression is associated with poor clinical prognosis and outcomes in patients with colorectal cancer (CRC) and oral squamous cell carcinoma (OSCC)." (PMID 27816970, 2017). "However, a high expression of HMGCS2 has been associated with the development of colorectal cancer (CRC) which is contrary to these findings." (PMID 37199828, 2023). "Expression of diagnostic markers was validated in vivo and in biospecimens, and our immunohistochemistry (IHC) results confirmed that HMGCS2 gradually decreased during the transformation of UC to colorectal cancer." (PMID 38633005, 2023). "Some researchers believe that HMGCS2 can be used as a monitoring indicator for the prognosis of colorectal cancer (CRC) and CRC radiotherapy and chemotherapy." (PMID 36419192, 2022). "We focused our attenuation on HMGCS2 expression, a rate- limiting enzyme that catalyzes the first reaction in ketogenesis, in human colorectal cancer tissue microarray by immunochemistry." (PMID 31355161, 2019). "What is more, according to TCGA data analysis, HMGCS2 expression in colorectal cancer, at mRNA levels, is significantly downregulated in tumors based on sample types, individual cancer stages, and histological subtype." (PMID 31355161, 2019). "The results showed that HMGCS2 expression is significantly reduced in colorectal cancer compared with healthy control, which is inversely correlated with MVD in colorectal cancer by IHC analysis." (PMID 31355161, 2019). "We aimed to seek evidence to elucidate the possible relationship between HMGCS2 expression and colorectal cancer prognosis." (PMID 31355161, 2019). "Our work revealed that HMGCS2 expression was drastically reduced in colorectal cancer tissue with enriched microvascular stained by CD31, and in vitro results found that depletion of HMGCS2 expression by siRNA transfection significantly increased tube formation." (PMID 31355161, 2019). "The study consisted of 100 cases with colorectal cancer and healthy control, the expression of HMGCS2 and the microvessel density (MVD) (marker: CD31) were analyzed by immunohistochemistry and tube formation, and the centration of β-hydroxybutyrate in serum was assessed by biochemical analysis." (PMID 31355161, 2019). "In addition, according to TCGA data, HMGCS2 expression in colorectal cancer, at mRNA levels, is significantly downregulated in tumors." (PMID 31355161, 2019). "Interestingly, we found enrichment of microvessel density in colorectal cancer tissue with lower HMGCS2 expression." (PMID 31355161, 2019). "Reduction of HMGCS2 expression was correlated with tumor angiogenesis in colorectal cancer tissues compared with normal tissue, displaying a negative clinical relationship." (PMID 31355161, 2019). "In addition to PKM2, PFKFB3, and FASN, there are no available reports about the role of HMGCS2 and angiogenesis in various cancers, including colorectal cancer." (PMID 31355161, 2019).
fatty liver disease (9 papers, 2016 to 2025). A reversible condition wherein large vacuoles of triglyceride fat accumulate in liver cells via the process of steatosis. "Among these critical enzymes in the ketogenic pathways, HMGCS2 is notably implicated in dysregulated ketogenesis in fatty liver disease." (PMID 39403635, 2024). "In addition, protein changes in HMGCS2 are associated with aberrant ketogenesis and subsequent development of fatty liver disease." (PMID 40664891, 2025). "Together, the phenotypic rescue of hepatosteatosis in postnatal Hmgcs2-KO mice by a transition to a low-fat, high-carbohydrate diet suggests that a fat-enriched dietary composition is required for ketogenic deficiency-induced fatty liver disease." (PMID 35421611, 2022). "For example, PPARα knockout mice, which exhibit impaired ketogenesis with decreased ketogenic enzymes, Hmgcs2 and Bdh1, develop hepatic steatosis." (PMID 39403635, 2024). "Here, we show that ketogenic insufficiency via disruption of hepatic HMGCS2 exacerbates liver steatosis in fasted chow and high-fat-fed mice." (PMID 37503004, 2023). "The implication of ketogenesis in the development and progression of fatty liver disease is further supported by our study using Hmgcs2-HET mice that exhibited reduced ketogenic function." (PMID 35421611, 2022). "Here we aimed to determine the impact of Hmgcs2-mediated ketogenesis and its modulations on the development and treatment of fatty liver disease." (PMID 35421611, 2022). "Future studies investigating HMGCS2's biology and regulatory mechanism would improve the ketogenesis-based therapeutic strategy against fatty liver disease." (PMID 35421611, 2022). "The significantly abnormal acetylation level of HMGCS2 in fatty livers indicated a ketone metabolism disorder in dairy cows with fatty liver disease." (PMID 32586350, 2020). "Additionally, mTORC1, which suppresses Hmgcs2 expression and ketogenesis by inhibiting the transcriptional activity of PPARα, is frequently activated in fatty liver disease." (PMID 39403635, 2024). "In infants, deficiencies in HMGCS2 or HMGCL lead to hepatomegaly and hepatic steatosis." (PMID 39403635, 2024). "•Postnatal mice lacking Hmgcs2 showed ketogenic deficiency and spontaneously developed fatty liver disease." (PMID 35421611, 2022). "As such, utilization of tissue-specific Hmgcs2 knockout and overexpression in vivo models will be required in the future to examine the functional implication of extrahepatic ketogenic effects in the development and improvement of fatty liver, respectively." (PMID 35421611, 2022). "•HMGCS2 overexpression improved the high-fat diet-induced fatty liver disease in adult mice." (PMID 35421611, 2022). "As these results suggest a potentially divergent role of Hmgcs2-mediated ketogenesis in liver fibrosis and inflammation in contrast to lipid and glucose metabolism, careful assessments of the benefits and limitations of ketogenesis-mediated treatments against fatty liver diseases will be necessary." (PMID 35421611, 2022). "Interestingly, FGF21 overexpression partially restored the expression of PPARα and its target genes, Acox1, Hmgcs2 and Cpt1a in Creb3l3−/− mice, which might have helped to improve the hepatic steatosis." (PMID 27301791, 2016). "Investigations into key enzymes and regulators, such as HMGCS2, BDH1, PPARα, and mTORC1, highlight the intricate interplay between ketone body metabolism and fatty liver disease." (PMID 39403635, 2024). "Consistently, postnatal mice lacking Hmgcs2 gene spontaneously develop fatty liver disease." (PMID 39403635, 2024). "Consistently, the mRNA expression levels of fatty acid oxidation-related genes, including ACOX1, CPT1, HMGCS2, and PDK4, were increased in the livers of the MHY2013-treated db/db mice, indicating that the increased AMPK/β-oxidation signaling contributes to the improvement of hepatic steatosis." (PMID 28129657, 2017).
liver cancer (9 papers, 2019 to 2025). An epithelial or non-epithelial malignant neoplasm that arises from the liver. "Our study elucidates a new molecular mechanism underlying the crosstalk between HMGCS2 expression and a KD in cancer treatment, which provides more information for precision medicine in developing personalized anti-liver cancer strategies." (PMID 32635582, 2020). "Ketogenic diets, which increase HMGCS2 expression and promote ketogenesis in the liver, protect against liver cancer." (PMID 40305364, 2025). "HMGCS2 and ketone bodies not only protect against liver cancer but also sensitize liver cancer cells to the chemotherapeutic agent sorafenib." (PMID 40305364, 2025). "In summary, a clearcut evidence for the tumor-suppressive role of HMGCS2 and ketogenesis exists only for liver cancer." (PMID 40305364, 2025). "Most of the published research concerns cancer of the liver, the organ that normally has the most robust HMGCS2 expression." (PMID 40305364, 2025). "There is clear evidence for the protective role of HMGCS2 against liver cancer and for the efficacy of ketone bodies in suppressing cancer cell proliferation and migration, and hence tumor growth and metastasis." (PMID 40305364, 2025). "Taken together, this study characterized the impacts of HMGCS2 expression and KB treatment on sorafenib usefulness in liver cancer cells." (PMID 36432116, 2022). "In conclusion, this study defined the impacts of HMGCS2 expression and ketone body treatment on influencing the sorafenib sensitivity of liver cancer cells." (PMID 36432116, 2022). "Previously, we reported that HMGCS2 downregulation enhanced the proliferation and migration abilities of liver cancers." (PMID 32635582, 2020). "We found that HMGCS2 controls the proliferation and migration abilities of liver cancer cells by regulating the apoptosis, c-Myc/cyclin D1, and EMT signaling pathways and acts in a ketone-dependent manner." (PMID 32635582, 2020). "Our studies highlight the potential therapeutic strategy of targeting HMGCS2-mediated ketogenesis in liver cancer." (PMID 31779269, 2019). "In this study, we provided new insights into the mechanisms linking HMGCS2 downregulation-induced defects in ketone production with liver cancer cell proliferation and migration." (PMID 31779269, 2019). "To reveal the expression profiles of HMGCS2 during the development of HCC, we used a liver tissue array to compare HMGCS2 expression among normal tissues and tissues representing fatty degeneration, chronic hepatitis, nodular cirrhosis, and liver cancer." (PMID 31779269, 2019). "However, SLC38A4 has been reported to function as a tumor suppressor in liver cancer through its modulation of Wnt/β-catenin/MYC/HMGCS2 axis acativation." (PMID 36599932, 2023). "In liver cancer, HMGCS2 expression was lower in HCC tissues." (PMID 36432116, 2022). "In addition, ketone body supplementation reduced the proliferation and migration ability of HMGCS2 knockdown liver cancer cells." (PMID 31779269, 2019). "Regulating HMGCS2-mediated ketone production in HCC may therefore represent a new treatment strategy for liver cancer." (PMID 31779269, 2019). "The expression of HMGCS2 in cancer varies; the modulation of ketone production through HMGCS2 in HCC is a potential therapeutic strategy for liver cancer." (PMID 39453509, 2024). "In this study, we first found that curcumin induced changes in the expression of CYP1A1, HMGCS2, HMOX1, LCN2, and MTTP, which are enriched in metal ion homeostasis, in all three liver cancer cell lines." (PMID 36838613, 2023). "Parallelly, DKO in MycOE mice also displayed suppression of liver cancer development compared to littermate control mice.Trmt6/Trmt61a DKO reduced levels of m1A, Pparδ, and Hmgcs2 in MycOE or DEN induced liver tumor tissues." (PMID 34728628, 2021).
liver cancer (continued). "On the basis of the expression of the newly edited and generated ED_miR-3144(3_A < G) target gene was reduced as liver cancer progressed, five candidates, INMT, GHR, GLYAT, SLC38A4, and HMGCS2, were identified through target prediction and expression pattern analyses." (PMID 36599932, 2023).
diabetic cardiomyopathy (7 papers, 2020 to 2025). Diabetic cardiomyopathy is a disorder of the heart muscle in people with diabetes. "Silencing peroxisome proliferator-activated receptor alpha reduces HMGCS2 expression and alleviates myocardial injury in diabetic cardiomyopathy." (PMID 40361044, 2025). "In particular, studies have shown that HMGCS2 expression is elevated in diabetic cardiomyopathy, contributing to disease progression." (PMID 40361044, 2025). "Recent data indicated that high HMGCS2 expression caused reactive oxygen species (ROS) accumulation and loss of the mitochondrial membrane potential (MMP), which then induced diabetic cardiomyopathy." (PMID 36629048, 2023). "A stimulatory role of PPARG on HMGCS2 expression has been observed, for example, in a mouse model of diabetic cardiomyopathy and in intestinal tumor cell lines and normal intestinal organoids." (PMID 32277923, 2020). "Hmgcs2 overexpression was reported to promote cardiomyocyte apoptosis, inflammation, and oxidative stress, whereas its silencing attenuates these effects in diabetic cardiomyopathy cell models." (PMID 41007634, 2025).
cardiomyopathy (6 papers, 2021 to 2025). A disease of the heart muscle or myocardium proper. "Twelve of the 52 mouse models identified with cardiomyopathy (Acadv1, Fxn, Mto1, Taco1, Hmgcs2, Mpv17, Opa1, Pnpla8, Tmem126b, Gpd2, Mpv17, Micu1) showed that the presence of cardiomyopathy can be dependent on the degree of stress." (PMID 37103033, 2023). "Studies also showed that HMGCS2 expression was elevated in right ventricles from patients with cardiomyopathy." (PMID 35506308, 2022). "The reduced JPH2 expression levels could be reversed by swimming exercise and silencing of 3-hydroxy-3-methylglutaryl-CoA synthase 2 (HMGCS2), suggesting that the cardiomyopathy development itself led to loss of JPH2." (PMID 35001666, 2022). "However, study has shown that the Hmgcs2 overexpression is related to myocardial lipotoxicity caused by a high-fat diet in mice, and the inhibition of the upregulation of Hmgcs2 can reverse cardiomyopathy induced by lipotoxicity." (PMID 35370704, 2022). "Recent findings suggest that exercise-mediated cardioprotection through upregulation of miR-344g-5p, which targets Hmgcs2 mRNA, blocks upregulation of HMGCS2 and thus protects against HFD-induced cardiomyopathy." (PMID 33647884, 2021).
esophageal squamous cell carcinoma (6 papers, 2017 to 2024). Esophageal squamous cell carcinoma (ESCC) is a type of esophageal carcinoma (EC) that can affect any part of the esophagus, but is usually located in the upper or middle third. "HMGCS2 was underexpressed were subsequently verified, which can be served as biomarkers for Esophageal squamous cell carcinoma." (PMID 29262657, 2017). "A study analyzing HMGCS2 levels in patients with esophageal squamous cell carcinoma (ESCC) revealed significant downregulation in primary ESCC, correlating strongly with patient prognosis." (PMID 38983924, 2024).
steatosis (6 papers, 2019 to 2025). Increased lipid within the cytoplasm of cells. "Congenital deficiency of the fate-committing enzyme of ketogenesis, 3-hydroxymethylglutaryl-CoA (HMG-CoA) synthase 2 (HMGCS2), is linked to hepatomegaly and steatosis." (PMID 40272888, 2025). "Loss of HMGCS2 predisposes the liver to steatosis and dysregulated hepatic energy metabolism." (PMID 40272888, 2025). "In particular, a reduction in Plin2 immunostaining, which emphasizes small lipid droplets, depicted a shift from diffuse microvesicular steatosis to focal macrovesicular steatosis at liver tissue periphery in early-wean Hmgcs2-KO mice, associated with better clinical outcomes of fatty liver." (PMID 35421611, 2022). "H&E and Plin2 staining of liver sections at p14 further confirmed the accumulation of small lipid droplets (microvesicular steatosis) in the hepatocytes of Hmgcs2-KO mice." (PMID 35421611, 2022). "Histological evaluation confirmed reductions in liver fat quantification and NAS steatosis score with early weaning in Hmgcs2-KO mice." (PMID 35421611, 2022). "NAFLD mice showed evident steatosis, fibrosis, and liver injury, and an increased expression of HMGCS2, Wnt3a/ β-catenin, and phosphorylated (p)-AMPK in the liver." (PMID 33647884, 2021). "This study demonstrated that 8 weeks of exercise prevented lipotoxicity-induced hepatic injury, inflammation, and steatosis by inhibiting HMGCS2, subsequently ameliorating apoptosis and normalizing the Wnt3a/β-catenin pathway." (PMID 33647884, 2021). "Similarly, VPCK/VCS ratio was decreased in steatosis- and injury-prone HMGCS2-Liver-KO mice, and VCS/VEGP ratio was increased." (PMID 40272888, 2025). "Importantly, H&E and Plin2 stainings of liver sections showed greater hepatosteatosis, specifically microvesicular steatosis, in Hmgcs2-HET mice compared to WT mice." (PMID 35421611, 2022). "H&E and Plin2 staining of p21 liver sections revealed that, in contrast to the severe microvesicular steatosis seen in Hmgcs2-KO mice at suckling, the livers of Hmgcs2-KO early-wean mice exhibited a significant reduction in lipid accumulation, making their phenotype comparable to those of WT mice." (PMID 35421611, 2022). "Formal histological evaluation of H&E-stained liver sections revealed higher liver fat quantification and NAFLD activity score (NAS), particularly in the steatosis component, in Hmgcs2-KO mice compared to WT and HET mice, while no ballooning and inflammation were observed." (PMID 35421611, 2022).
Hypoglycemia (5 papers, 2019 to 2025). A decreased concentration of glucose in the blood. "Mitochondrial HMG‐CoA synthase‐2 (HMGCS2) deficiency is characterized by hypoketotic hypoglycemia, metabolic acidosis, hepatomegaly, and encephalopathy with onset between 3 and 36 months of age." (PMID 40548098, 2025). "A reanalysis 3 years later with an additional phenotype, hypoglycemia (HP:0001943), revealed a homozygous pathogenic variant in the HMGCS2 gene, designated as c.1502G>C (p.Arg501Pro)." (PMID 40548098, 2025). "In addition, patients having mitochondrial HMG-CoA synthase 2 (HMGCS2) deficiency, a rare autosomal recessive disorder of ketogenesis attributed to mutation of HMGCS2, also show fasting hypoglycemia and metabolic acidosis." (PMID 38604598, 2024). "During starvation, the hypoglycemia and the following lipemic response increase HMGCS2 expression in the liver in order to support the brain with fuel in the form of ketone bodies." (PMID 35565929, 2022). "Homozygous variants in human HMGCS2 are well known to cause the very rare metabolic disorder HMGCS2 deficiency (OMIM: 605911), which is characterized by severe hypoketotic hypoglycemia, encephalopathy, and hepatomegaly that is triggered after extended periods of fasting or after infections." (PMID 31910233, 2020). "Importantly, 1,3-BD administration ameliorated fasting hypoglycemia in PPARα−/− mice by increasing the blood BHB concentration without transactivation of hepatic Hmgcs2 expression." (PMID 38604598, 2024).
Obesity (5 papers, 2016 to 2025). Accumulation of substantial excess body fat. "In contrast, intestinal Hmgcs2 was strongly induced in both WT and DIO mice, with Oxct1 upregulated only in obesity, indicating local ketone production and consumption." (PMID 41156456, 2025). "They showed that some lipid metabolism-related genes (i.e., Mod1, Cyp4a10, Hmgcs2, Acot1, Acot2, Pdk4, Acaa1b, Cpt1, Fabp1, and Acadl) were significantly up-regulated in the intestine of both A/J (obesity-resistant) and C57BL/6J (obesity-prone) mice fed with high fat diet." (PMID 26861690, 2016).